RPS29 (ribosomal protein S29)
Description:
Component of the small ribosomal subunit. The ribosome is a large ribonucleoprotein complex responsible for the synthesis of proteins in the cell.
Synonyms: S29; uS14; DBA13
Tractability: Small molecule: an approved drug acts on it; a structure with a bound ligand is known; a high-quality ligand is known. PROTAC: ubiquitination databases record sites on it; its protein half-life has been measured; a small molecule that binds it is known. Other modalities: a drug acting on it is in phase 2 or 3 trials.
Target class: Other cytosolic protein
Gene: Protein-coding gene on chromosome 14 (49,570,984 to 49,599,164, reverse strand). Ensembl gene ENSG00000213741.
Subcellular location: Cytoplasm, cytosol; Cytoplasm; Rough endoplasmic reticulum
Subcellular location (Human Protein Atlas): Cytosol; Endoplasmic reticulum
Pathways (Reactome):
Metabolism of proteins: Eukaryotic Translation Termination; Formation of a pool of free 40S subunits; Formation of the ternary complex, and subsequently, the 43S complex; GTP hydrolysis and joining of the 60S ribosomal subunit; L13a-mediated translational silencing of Ceruloplasmin expression; PELO:HBS1L and ABCE1 dissociate a ribosome on a non-stop mRNA; Peptide chain elongation; Ribosomal scanning and start codon recognition; SRP-dependent cotranslational protein targeting to membrane; Translation initiation complex formation; ZNF598 and the Ribosome-associated Quality Trigger (RQT) complex dissociate a ribosome stalled on a no-go mRNA
Disease: SARS-CoV-1 modulates host translation machinery; SARS-CoV-2 modulates host translation machinery; Viral mRNA Translation
Metabolism of RNA: Major pathway of rRNA processing in the nucleolus and cytosol; Nonsense Mediated Decay (NMD) enhanced by the Exon Junction Complex (EJC); Nonsense Mediated Decay (NMD) independent of the Exon Junction Complex (EJC)
Cellular responses to stimuli: Response of EIF2AK4 (GCN2) to amino acid deficiency
Developmental Biology: Regulation of expression of SLITs and ROBOs
Metabolism: Selenocysteine synthesis
Gene Ontology:
Molecular function: structural constituent of ribosome; zinc ion binding
Biological process: cytoplasmic translation; translation
Cellular component: cytosol; cytosolic small ribosomal subunit; endoplasmic reticulum; extracellular exosome; focal adhesion; ribosome; small ribosomal subunit; cytoplasm; cytoplasmic side of rough endoplasmic reticulum membrane; nucleoplasm; rough endoplasmic reticulum; cytosolic ribosome
Genetic constraint (gnomAD): Loss-of-function variants: 0 observed, 9.7 expected, observed/expected ratio (o/e) 0, 90% interval 0 to 0.31. That is too few expected variants to judge how well the gene tolerates losing a copy. Missense variants: 56 observed, 79.2 expected, observed/expected ratio (o/e) 0.71, 90% interval 0.57 to 0.88. Synonymous variants: 37 observed, 28.11 expected, observed/expected ratio (o/e) 1.32, 90% interval 1.01 to 1.72.
Homologues: Orthologues: rabbit RPS29 (100% identical), rat Rps29-ps15 (100% identical), tropical clawed frog rps29 (100% identical), zebrafish rps29 (96% identical), Drosophila melanogaster RpS29 (79% identical), Caenorhabditis elegans rps-29 (73% identical).
Diseases named in the same sentence as RPS29 in open-access papers:
RPS29 is named in the same sentence as 33 diseases in open-access papers, as found by Europe PMC text mining. Sharing a sentence is not in itself a finding about the gene and the disease. The quoted sentences say what the papers report.
COVID-19 (3 papers, 2020 to 2023). A disease caused by infection with severe acute respiratory syndrome coronavirus 2. "To explore the relationship between immune situation and RPS29 expression, we divided the COVID-19 patients into two groups (low expression group and high expression group) according to the median value of RPS29 expression." (PMID 37063869, 2023). "Further WGCNA analysis suggested that ribosomal dysfunction may play a key role in brain dysfunction in elderly COVID-19 patients, with RPS29, S100A10, and TIMP1 as key molecules." (PMID 37063869, 2023). "Additionally, differential expression of RPS29 may partially react to the differential expression of RPS29 following vaccination in patients with COVID-19." (PMID 36936955, 2023). "RPS29, S100A10, and TIMP1 were the critical genes in the brain pathology of COVID-19 in elderly patients." (PMID 37063869, 2023). "Interestingly, TIMP-1 is the most related differential gene between RPS29 and S100A10, these results demonstrate the presence of intracranial inflammatory response in COVID-19 patients." (PMID 37063869, 2023). "In addition, it is likely that a combination of RPS29 and SPAG9 genes induced pathways, as well as downregulation of cardioprotective genes, contribute to cardiac and vascular events in patients with COVID-19." (PMID 33240937, 2020).
Diamond-Blackfan anemia (3 papers, 2019 to 2022). A congenital aregenerative and often macrocytic anemia with erythroblastopenia. "Germ-line mutation in RPS29 cause Diamond-Blackfan anemia, which is an inherited bone marrow failure syndrome." (PMID 33240937, 2020). "There are abundant genetic and experimental evidences demonstrate that Diamond-Blackfan anemia (DBA), a dominant autosomal bone marrow failure syndrome, is due to mutations in ribosomal genes including RPS19, RPS24, RPL5, RPL11, and RPS29, etc8-12." (PMID 31523176, 2019).
colorectal cancer (2 papers, 2009 to 2023). A primary or metastatic malignant neoplasm that affects the colon or rectum. "Because FIRΔexon2 is detected in colorectal cancer tissues, the expressions of RPL30, RPL37A, RPL38, RPS14, and RPS29 mRNAs by the effect of FIRΔexon2 were examined in HCT116 cells." (PMID 38139171, 2023).
laryngeal carcinoma (2 papers, 2015 to 2022). Carcinoma that arises from the laryngeal epithelium. "S29 ribosomal protein (RPS29) has been shown to induce mitochondrial-mediated apoptosis of the human laryngeal carcinoma cell line (Hep2 cells) through the activation of p38 MAPK and JNK signaling." (PMID 25675329, 2015).
lymphoma (2 papers, 2016 to 2022). A malignant (clonal) proliferation of B- lymphocytes or T- lymphocytes which involves the lymph nodes, bone marrow and/or extranodal sites. "RPS29 upregulation was observed only in lymphoma cells, suggesting a targeted function in oncogenesis." (PMID 36226068, 2022). "Besides lymphoma, raised free levels of several RPs (RPS15A, RPL23A, RPS26 and RPS29) have been associated with aggressiveness and bad prognosis also in other malignancies." (PMID 36226068, 2022). "Interestingly, precisely the opposite pattern is observed when comparing RPS29 and RPS27L expression in cell-line models of lymphoma/lymphoid leukemia, which represent intermediate developmental stages, and mature lymphocytes." (PMID 27884178, 2016).
acute myocardial infarction (1 paper, 2020). Necrosis of the myocardium, as a result of interruption of the blood supply to the area. "RNA-seq analysis of acute myocardial infarction samples has shown that RPS29 was one of the top upregulated genes." (PMID 33240937, 2020).
breast carcinoma (1 paper, 2022). "Cluster 1 and cluster 2 had no specific enriched breast cancer signatures however cluster 1 had several ribosomal and ER stress-associated genes (Rpl41, Rps27, Rps29, Fosb, and Jund)." (PMID 35851387, 2022).
cervical dysplasia (1 paper, 2021). "Five out of ten consistently upregulated genes (CEBPD, KRT16, SLPI, RPS29, and PPL) were also increased in cervical dysplasia." (PMID 34944802, 2021). "Unlike CEBPD, SLPI, KRT16, and RPS29, NOTCH1 expression in these cell lines did not match the increase seen in cervical dysplasia and cancer samples in silico." (PMID 34944802, 2021).
co-infection (1 paper, 2018). "These functions provide clues about the theoretical consequences that the sequestering of RPSA and RPS29 by the CRE might entail, such as avoiding co-infection with other members of the Flaviviridae family or the induction of hepatocarcinoma." (PMID 30382192, 2018).
Cognitive impairment (1 paper, 2025). Abnormal cognition is characterized by deficits in thinking, reasoning, or remembering. "Prolonged hypoxia triggers Rps29‐Bax‐mediated apoptosis and Tnfrsf21‐App‐driven neuroinflammation, culminating in myelin loss and cognitive impairment." (PMID 40546220, 2025).
Hyperglycemia (1 paper, 2024). An increased concentration of glucose in the blood. "In diabetic mother, ten Hub genes (RPL36, RPS29, RPL8 and so on) are key factors in the increased macrosomia in hyperglycemia." (PMID 38660519, 2024).
iron deficiency (1 paper, 2021). "Based on our results, rRNA (Rpl19 and Rps29) are the most stable and highest ranking RG for the weanling model of iron deficiency." (PMID 34600467, 2021). "Based on the ten-selected RG, Rpl19 and Rps29 are the most suitable RG for normalization studies involving gastrocnemius, heart, kidney, liver, lung, and spleen tissues in studies focused on the male weanling model of dietary iron deficiency." (PMID 34600467, 2021).
non-small cell lung carcinoma (1 paper, 2006). A group of at least three distinct histological types of lung cancer, including non-small cell squamous cell carcinoma, adenocarcinoma, and large cell carcinoma.
osteoarthritis (1 paper, 2022). A noninflammatory degenerative joint disease occurring chiefly in older persons, characterized by degeneration of the articular cartilage, hypertrophy of bone at the margins and changes in the synovial membrane. "In recent single-cell sequencing work, it was demonstrated that increased RPS29 (ribosomal protein S29) expression in chondrocytes is associated with osteoarthritis progression [16▪]." (PMID 34750309, 2022).
osteosarcoma (1 paper, 2021). A usually aggressive malignant bone-forming mesenchymal neoplasm, predominantly affecting adolescents and young adults. "Our results showed that compared with osteoblasts, CPEB3, EIF4E3, RBM34, RPS27L, RPS29 and TDRD6 were down-regulated in U2OS and 143B, while NXT2, TERT, TLR8 and ZC3HAV1 were up-regulated in osteosarcoma cells." (PMID 34926575, 2021).
posttraumatic stress disorder (1 paper, 2020). "Among these genes, the ribosomal protein S29 gene (RPS29) showed a marginal significant association in a genome-wide association study with posttraumatic stress disorder." (PMID 32223758, 2020).
cancer (6 papers, 2009 to 2026). A tumor composed of atypical neoplastic, often pleomorphic cells that invade other tissues. "RPS29 mRNA may be upregulated irrespective of HPV status and because of indiscriminate cancer pathways." (PMID 34944802, 2021).
tumor (4 papers, 2009 to 2024). "RPS29, in contrast, enhances the tumour suppressor activity of the Ras-related protein 1A40." (PMID 30382192, 2018). "It should be noted that the median expression ratio between tumor tissue and matched normal mucosa was very low with a maximum over-expression of 1.4-fold for ACT and RPS29 and a maximum expression decrease of 1.7-fold for GAPDH and HPRT." (PMID 19650912, 2009). "These expression levels were lower in tumor than in normal samples for ACT and RPS29 (Wilcoxon test for paired data, p < 0.05)." (PMID 19650912, 2009).
RPS29 also shares sentences with these, for which no sentence is quoted: infection (2 papers); bone marrow failure syndrome (1); cardiovascular disease (1); cervical cancer (1); depression (1); gastric cancer (1); head and neck squamous cell carcinoma (1); hearing loss (1); lymphoid leukemia (1); macrosomia (1); Nephroblastoma (1); parasitic infections (1); prostate carcinoma (1); virus infection (1); Waldenstrom macroglobulinemia (1).